MACC1 (MET transcriptional regulator MACC1)
Diseases named in the same sentence as MACC1 in open-access papers (continued):
Sharing a sentence is not in itself a finding about the gene and the disease.
tumor (continued). "The potenial correlation of MACC1 and c-Met expression to tumor cell proliferation and apoptosis was also analyzed." (PMID 23414367, 2013). "We found MACC1 nuclear expression were associated with poor HCC differentiation (p = 0.0185) and larger tumor size (p = 0.0175)." (PMID 23414367, 2013). "In cohorts 1 and 2, 55.5% and 60.0% of patients exhibited high levels of MACC1 expression in their tumor samples, respectively, while, the remaining 44.5% and 40.0% of tumor samples exhibited low expression of MACC1." (PMID 23497677, 2013). "In our univariate analysis, stepwise inclusion of variables in the model showed that significant prognostic factors included MACC1 level, tumor size and TNM classification." (PMID 23717574, 2013). "Immunohistochemical results showed that the positive rate of MACC1 in the 98 tumor tissues was 61.22% (60/98)." (PMID 24325214, 2013). "In the clinical subgroup with one single HCC tumor nodule, the 5-year survival rates were 54% and 13%, respectively, for low- or high-MACC1 expression patients (P<0.001)." (PMID 23717574, 2013). "We found significantly higher MACC1 levels in colon, rectal, and colorectal (combined) cancer patients compared to tumor-free individuals (all P<.001)." (PMID 23166620, 2012). "We analyzed the association of the MACC1 SNPs with clinical parameters such as age, gender as well as with metachronous metastasis, UICC-stages, tumor and lymph node infiltration." (PMID 22838389, 2012). "Specifically, lower expression of APC, DCC, and DSC2 and higher expression of MACC1 was observed in the tumor samples relative to the paired adjacent normal tissue in both the microarray and qPCR assays." (PMID 22363440, 2012). "In the present study, we confirmed the regulatory relationship between miR-143, a known tumor suppressive miRNA, and a new oncogene, MACC1." (PMID 22533346, 2012). "We analyzed the basal MACC1 levels of tumor-free volunteers in two independent cohorts (n = 34 and n = 20, respectively)." (PMID 23166620, 2012). "Using both in silico prediction and western blot assay, we found the previously reported tumor suppressive miR-143 targeted MACC1 in CRC." (PMID 22533346, 2012). "Existing data regarding the involvement of MACC1 in tumor metastasis also suggest its particular therapeutic impact." (PMID 22533346, 2012). "Plasma separation and subsequent MACC1 analyses were performed immediately or 7, 24, 48, and 72 hours after blood taking from tumor-free volunteers (n = 12; 10 aliquots per volunteer), either 4°C-cooled or left at room temperature." (PMID 23166620, 2012). "In xenograft model study, they showed that knockdown of MACC1 by si/shRNA resulted in significant reduction of tumor size and number of liver metastases." (PMID 22533346, 2012). "Levels of circulating MACC1 transcripts are significantly higher in cancer patients compared to tumor-free volunteers." (PMID 23166620, 2012). "Taken together, these results indicated that miR-143 functions as a potent tumor suppressor through regulating MACC1 expression." (PMID 22533346, 2012). "MACC1 transcript levels are increased in all disease stages of the cancer patients compared to tumor-free volunteers." (PMID 23166620, 2012). "The relationships of MACC1 with other signalling molecules and pathways must be further evaluated to better understand the molecular pathogenesis of these tumours and develop more effective targeted therapeutic strategies." (PMID 21955323, 2011). "MACC1 has emerged as a potential biomarker that could serve as a valuable predictor for tumor metastasis and patient prognosis across a spectrum of cancers." (PMID 41239615, 2025). "The expression of MACC1 was significantly correlated with the degree of tumor differentiation." (PMID 41239615, 2025). "In addition to inducing tumor cell migration, MACC1 is also closely related to cytoskeleton and adhesion system." (PMID 40354443, 2025).
tumor (continued). "Furthermore, we discovered that the overexpression of MACC1 exhibited a positive correlation with tumor histological grade, TNM staging, and LNM staging." (PMID 41239615, 2025). "To investigate the effect of MACC1 on tumor, we transfected EC cells with MACC1-siRNA." (PMID 40354443, 2025). "MACC1, prevalent in various solid tumors, has emerged as a predictor in tumor stages." (PMID 39399490, 2024). "Metastasis-associated in colon cancer 1 (MACC1) is a novel prognostic biomarker for tumor progression and metastasis formation independent of tumor stage." (PMID 38339354, 2024). "Here, the ectopic manipulation (up- or downregulation) of MACC1 translated into corresponding changes of PD-L1, and ultimately into alterations of the anti-tumor effects and immune cell-mediated killing capacity of peripheral blood mononuclear cells (PBMCs) in a co-culture setting." (PMID 38611008, 2024). "Above findings suggest MACC1 has a potential oncogenic role in tumor progression." (PMID 39695175, 2024). "Since CSCs are believed to be responsible for tumor metastasis and relapse, interventional combinatorial approaches targeting MACC1 and LGR5 will potentially improve further targeted therapies for CRC patients to eradicate CSCs and prevent cancer recurrence and distant metastasis formation." (PMID 38339354, 2024). "Inhibition of MACC1 expression could potentially lead to significant anti-tumor effects by disrupting key molecular pathways involved in tumor growth, angiogenesis, and metastasis." (PMID 39273182, 2024). "We observed significantly increased tumor sphere formation in high-MACC1-expressing cells." (PMID 38339354, 2024). "Besides, MACC1 has been reported to promote tumor immune escape via upregulating PDL1 (Programmed cell death ligand 1) expression." (PMID 39695175, 2024). "However, there is only limited data of MACC1 as a biomarker of immune system status and anti-tumor immunity." (PMID 38611008, 2024). "MACC1 prominently enhances tumor cell migration and also inhibits immune surveillance." (PMID 38396744, 2024). "In addition, MACC1 can also induce tumor progression in transgenic mice and colorectal cancer patients by activating stemness protein markers Oct4 and Nanog." (PMID 39695175, 2024). "All tumor types were found to express MACC1, though to variable degrees." (PMID 36979146, 2023). "However, when diminishing GIPC1 expression in endogenously MACC1 high expressing cells, spleen tumor development and liver metastasis formation are reduced." (PMID 38144523, 2023). "We then evaluated associations between MACC1 or MET expressions and tumor progression." (PMID 37496665, 2023). "Thus, this review aims to summarize the different downstream effects of MACC1 on tumor migration and how these can be integrated into the cytoskeletal and adhesive systems." (PMID 37051546, 2023). "Atypical DNA methylation may play a significant role in the variability in MACC1 expression in various tumor types." (PMID 36979146, 2023). "Interestingly, Macc1 silencing resulted in significantly lower cell viability in the knock down tumor cells (siMacc1) compared to T1 tumor cells (Control)." (PMID 37841442, 2023). "Lastly, open questions about MACC1-dependent effects on tumor cell migration will be addressed." (PMID 37051546, 2023). "In summary, there are clear hints on the effects of MACC1 acting on cell–matrix adhesions, but the effects may depend on the tumor type, analyzed integrins, or the ECM component, and consequently, this aspect needs additional research for a clear picture." (PMID 37051546, 2023). "Interestingly, circulating MACC1 transcripts or protein levels can also serve as predictive markers for tumor progression, as demonstrated in patients with colorectal, pancreatic, gastric, lung, and breast cancer." (PMID 37051546, 2023).
tumor (continued). "Since a previous study demonstrated that MET is a key transcriptional target gene of MACC1 in multiple cancers and contributes to tumor progression, we wanted to determine whether MACC1 plays a critical role in PC metastasis via MET." (PMID 36333284, 2022). "The high level of MACC1 enhances the clonogenicity of the tumor cells." (PMID 36432477, 2022). "The high expression of MACC1 and cyclin D1 was significantly correlated with tumor size." (PMID 35242498, 2022). "We hypothesized that MACC1-overexpressing tumor cells stimulate cell migration by secretion of pro-metastatic factors." (PMID 36008464, 2022). "In addition, the expression of MACC1 correlated positively with tumor immune cell infiltration, as well as with the levels of biomarkers of five kinds of immune cells." (PMID 36545127, 2022). "MACC1 is an enhancer of tumor aggressiveness and a predictor of poor survival in AGE/S." (PMID 35406545, 2022). "MACC1 expression level is the main parameter, determining all these phenotypes, which can be determined at RNA and/or protein level using different technologies in tumor tissue and/or patient blood (cell-free RNA, circulating tumor cells)." (PMID 35406521, 2022). "As both intracellular S100P expression levels and high abundance of extracellular S100P can promote tumour progression and metastasis, we tested if the MACC1-mediated expression of S100P in CRC cells also leads to an increase in extracellular S100P protein levels." (PMID 35597866, 2022). "Curcumin reduced the MACC1 expression, restricted the MACC1-induced proliferation, and was able to reduce the MACC1-induced cell motility as one of the crucial steps for the distant dissemination of the tumor." (PMID 36432477, 2022). "Although MACC1 possesses various modes of action to foster tumor metastasis, a functional insight whether and how tumor cell communication with the cellular microenvironment is affected by MACC1 remains elusive." (PMID 34830078, 2021). "No obvious association between the expression of MACC1 and clinicopathological parameters was observed in terms of age (P = .84), tumor size (P = .56) or ascites (P = .79)." (PMID 33663046, 2021). "Furthermore, the possible correlation between MACC1 expression and the different immune cells in the tumor microenvironment was explored." (PMID 34577857, 2021). "We also analyzed the co-expression of MACC1 and tumor-related genes through the GEPIA database." (PMID 34343214, 2021). "MiR-338-3p functions as a tumor suppressor through MACC1 inhibition in CRC." (PMID 33827418, 2021). "The expression levels of MACC1 in primary CRC lesion may better reflect the character of tumor total lesion glycolysis." (PMID 33750337, 2021). "Given the correlation between MACC1 and EMT, and between EMT and tumor development, we hypothesized that MACC1 could be correlated with EMT in NPC malignancy." (PMID 33854976, 2021). "Clinically, this is reflected by an accumulation of MACC1 at the invasive front of tumor cells." (PMID 34830078, 2021). "Targeting either SP1 or miR-320a may be a potential strategy to prevent MACC1-driven tumor progression." (PMID 33731131, 2021). "The expression levels of GLUT-1 in CRC primary lesion may better reflect the character tumor glucose metabolism volume and MACC1 may reflect total lesion glycolysis." (PMID 33750337, 2021). "Besides its role in tumor development and metastasis, it was believed that MACC1 protects metastasis from immune destruction by modifying the tumor microenvironment (TME)." (PMID 34577857, 2021). "This correlation could be explained as the expression of MACC1 is related to tumor progression, overexpressed MACC1 enhanced the tumor Warburg effect that increasing the glucose metabolism activity of CRC." (PMID 33750337, 2021). "Moreover, patients with high expression of MACC1 tended to suffer from worse tumor differentiation, more advanced clinical stage and earlier lymph node metastasis compared to those with low expression of MACC1." (PMID 33663046, 2021).
tumor (continued). "Since MACC1 is confirmed as decisive driver for tumor growth and metastasis in a variety of solid cancers, the findings made here for CRC might be translated to further solid tumor types." (PMID 34247190, 2021). "This suggests that in addition to promoting metastasis, MACC1 may also be closely related to tumor proliferation." (PMID 34343214, 2021). "Additionally, we noticed the expression of CD31 in tumor tissues from MACC1 depletion group was obviously decreased, compared to the control group, suggesting the decrease number of endothelial cells and confirmed our in vitro data." (PMID 33425885, 2020). "Importantly, our data also demonstrated that the expression of c-Met and HGF was reduced in MACC1-depleted tumor tissues, further confirming our previous findings." (PMID 33425885, 2020). "We found lnc-HSD17B11-1:1 and MACC1 are co-overexpressed in CRC tumor tissues." (PMID 32595704, 2020). "Importantly, however, high MACC1 expression was correlated with high microvessel density (p = 0.020) and tumor volume (p = 0.002)." (PMID 33425885, 2020). "Besides increased cell proliferation and motility, subsequently contributing to growth and metastatic spread of the primary tumor, MACC1 has also been shown to dysregulate apoptosis and is contributing to treatment resistance." (PMID 32391276, 2020). "MACC1 was previously shown to increase migration in many tumor types, including GBM." (PMID 32503676, 2020). "Moreover, we analyzed the prognostic stratification effects of MACC1 index (median) on various clinical parameters including sub-histological tumor type, gender of the patient and age, TNM status and AJCC stages." (PMID 30805302, 2019). "Furthermore, silencing of MACC1 led to an increase in antitumor and immune killing in vitro and in vivo, and overexpression of MACC1 resulted in a decrease in tumor immunity in vitro and in vivo." (PMID 31557409, 2019). "Moreover, higher plasma MACC1 levels were positively correlated to the tumour status of N1 or N2, M1 and AJCCIII+IV, and also in died CRC patients." (PMID 30370603, 2019). "Previous studies have demonstrated that MACC1 can promote tumor cell proliferation and migration." (PMID 30021598, 2018). "MACC1+ expression was also associated with tumor grade, LNM, implantation and FIGO stage, but not patient age, tumor location, size, type, or ascites." (PMID 28253891, 2017). "Simultaneously, YB-1 knockdown inhibited the expression of MACC1 in tumor tissues." (PMID 28624808, 2017). "Therefore, finding effective MACC1 inhibitors will add to the therapeutic possibilities for targeted intervention of tumor progression and metastasis progression." (PMID 28570591, 2017). "Furthermore, depletion of YB-1 attenuated tumorigenesis in a xenograft mouse model and reduced MACC1 expression in tumor tissues." (PMID 28624808, 2017). "In CRC patients, MACC1 is a tumor stage-independent predictor for metastasis and survival." (PMID 27439755, 2016). "Thus, high expression of MACC1 in tumor specimens served as an independent prognostic marker for MFS." (PMID 27462788, 2016). "In silico analysis revealed MACC1 as a potential target of miR-218, a tumor suppressor miRNA." (PMID 27462788, 2016). "The association between serum MACC1 and clinical TNM staging in the current study may be explained by the fact that most serum MACC1 originates from tumor tissues." (PMID 27793048, 2016). "Our findings might be very relevant for the use of MACC1 for prognostication of unfavorable tumor progression and metastatic potential of colorectal lesions." (PMID 27439755, 2016). "The data of xenografts suggesting that the combination of trastuzumab with oxamate effectively inhibited tumor growth and the Warburg effect in vivo and MACC1 may demonstrate the synergistic inhibitory effect in HER2-positive GC." (PMID 27581375, 2016). "Initially, we tested whether change of MACC1 expression could influence the growth of tumor in vivo." (PMID 27280289, 2016).
tumor (continued). "Moreover, KAI1 is able to be bind to c-MET to form a complex or quench the activation of HGF, thus preventing the activation of MACC1 to inhibit the migration of tumor cells." (PMID 27793161, 2016). "In addition, the pooled results of TNM stage, nodal status, and tumor depth suggested that increased MACC1 expression promoted regional invasion and lymph-node metastasis, thus leading to poorer CRC prognosis." (PMID 27542234, 2016). "Investigation of associations between MACC1 or ALDH1 protein levels with clinicopathological parameters of NSCLC revealed correlations between the expression of each with tumor grade, lymph node metastasis, and tumor node metastasis." (PMID 27832750, 2016). "Furthermore, MACC1 expression was positively correlated with tumor size, grade, invasion of depth, LNM, and TNM stage." (PMID 27793161, 2016). "As a result, ectopic expression of MACC1 facilitated tumorigenesis in vivo: the average volume of the oxMACC1 tumors was markedly larger than that of the vector-controls at day 18, and shMACC1 injected mice displayed significantly minimal tumor volume." (PMID 27280289, 2016). "Ki-67 expression in tumor tissues was consistent with serum MACC1." (PMID 27793048, 2016). "Therefore, the present data from our studies indicate that MACC1 is an oncogenic enhancer for endothelium-dependent angiogenesis and tumor progression in GC." (PMID 27280289, 2016). "In tumor tissues, downregulation of the MACC1 post-transcriptional regulators, miR-218 and miR-338-3p, could be reasons for the MACC1 overexpression and its mediated EMT, cancer metastasis formation and drug resistance." (PMID 27462788, 2016). "Compared to PBS, trastuzumab could inhibit the tumor growth more effectively when MACC1 was downregulated." (PMID 27581375, 2016). "In addition to controlling the important events of cell proliferation and apoptosis, MACC1 is also involved in tumor cell invasion and metastasis." (PMID 26043756, 2015). "MACC1 was significantly over-expressed in tumor tissue as compared to normal mucosa (p < 0.001)." (PMID 25884643, 2015). "In fact, 18 of 19 patients with distant metastasis were correctly identified based on marker expression in this geographic area, indicating that MACC1 expression at the tumor host interface may be particularly important for tumor spread to distant organs." (PMID 25884643, 2015). "Based on the variety of detection methods, possibilities for assessment in tumor tissue and plasma and inclusion in early clinical trials, MACC1 is a promising candidate in the growing list of potentially valuable biomarkers to aid the identification of high risk CRC patients." (PMID 25884643, 2015). "At the tumor front, MACC1 expression was observed in 72.2% of cases." (PMID 25884643, 2015). "In the tumor center, MACC1 expression (score 1–3) was observed in 58.3% of cases." (PMID 25884643, 2015). "Studies confirmed that MACC1 plays tumor-promoting role, indicating that it might be a potential risk factor for adverse clinical outcome." (PMID 26090393, 2015). "In a novel geographic approach towards immunohistochemical MACC1 expression analysis on full tissue sections, we identify a progressive increase of MACC1 positivity from the tumor center towards the invasive front with frequent overexpression in tumor budding cells." (PMID 25884643, 2015). "In several xenograft mouse models, MACC1 induces tumor progression and metastasis." (PMID 25884643, 2015). "In contrast, silencing MACC1 can attenuate tumor cell growth and metastasis." (PMID 26090393, 2015). "In tumor buds, MACC1 expression correlated with aggressive disease biology." (PMID 25884643, 2015). "Furthermore, numerous studies have suggested that MACC1 induces tumor metastasis through the regulation of the hepatocyte growth factor (HGF)/MET signaling pathway." (PMID 26043756, 2015).